GPX4 (glutathione peroxidase 4)
Diseases named in the same sentence as GPX4 in open-access papers (continued):
Sharing a sentence is not in itself a finding about the gene and the disease.
tumor (continued). "We solved this problem of partial ferroptosis induction by the development of an inducible model of ferroptosis relying on the doxycycline-dependent knockdown of GPX4 allowing synchronized and complete cell death induction and did not result in the production of the tumor on the vaccination site." (PMID 35760796, 2022). "For example, inhibition of either DHODH or GPX4 alone did not induce ferroptosis in HT-1080 cells, which is likely due to the relatively high endogenous expression of GPX4 and DHODH; interestingly, a GPX4 inhibitor combined with a DHODH inhibitor could synergistically suppress HT-1080 tumor growth." (PMID 35814401, 2022). "Recently, Wang’s team discovered that the promoter region of GPX4 binds to cyclic adenosine monophosphate response element binding protein (CREB) and that this binding can be enhanced by E1A binding protein P300 (EP300), promoting tumor proliferation, migration, invasion and angiogenesis." (PMID 36105219, 2022). "The lack of GPX4 gene expression can prevent mouse tumor recurrence, but it is necessary to determine whether GPX4 is an oncogene further." (PMID 34975326, 2022). "Therefore, researchers assumed that tumor cells undergoing ferroptosis are likely to secrete more PGE2 because of the inactivation of GPX4, whereas tumor cells treated with chemotherapy would produce more PGE2, that in turn would promote the growth of ferroptosis‐sensitive tumor cells." (PMID 36317423, 2022). "We found that the expression of GPX4 in PANC-1 and BxPc-3 cells were both lower than in hTERT-HPNE cells, indicating that there was a certain degree of ferroptosis, which may be a self-adaptive response of tumor cells." (PMID 35288541, 2022). "In addition, emerging studies reveal that GPX4 inhibitors such as RSL-3 and ML162 efficiently suppress tumor growth, implying that GPX4 could be a promising target for tumor inhibition." (PMID 35882850, 2022). "In our study, we investigated an aberrantly upregulated gene in ESCC tumor tissues CARS1 significantly inhibited cell proliferation, and the ability of migration and invasion promoted the relative level of MDA and ROS and decreased GPX4 expression level in two ESCC cell lines." (PMID 36213827, 2022). "Erastin, first identified as killing tumor cells expressing oncogenic RAS, is a classical agent to induce ferroptosis by suppressing cystine/glutamate antiporter (xCT) and leading to decreased cysteine and then inhibiting the function of glutathione peroxidase 4 (GPX4)." (PMID 34745421, 2021). "In addition, inactivation of GPx4 could result in GSH depletion, thus promoting tumor-specific ferroptosis." (PMID 34691357, 2021). "Moreover, the degree of connectivity of GPX4, GZMA, and GZMB in the PPI network above was 4, 4, and 10, respectively, suggesting that GZMB may indeed be involved in tumor growth and progression in CC patients." (PMID 34837692, 2021). "Meanwhile, together with the directly amplified ROS production, the LPO accumulation could be indirectly promoted by destroying the antioxidative defense system of tumor cells through SRF-induced GSH and GPX4 reduction, which could further increase the oxidative stress within tumor sites." (PMID 34238297, 2021). "Thus, with the exception of tumor cells, oxytosis/ferroptosis in vivo is more likely to be induced by GPX4 inhibition rather than system xc- inhibition." (PMID 29731704, 2018).
tumor (continued). "In addition, the research team discovered a positive correlation between CD86 expression and the immune checkpoint PD‐1/TIM‐3 expression, while overexpression of GPX4 could inhibit lipid peroxidation induced by ox‐LDL, rescuing T cells from ferroptosis and restoring their anti‐tumor function." (PMID 41560416, 2026). "However, GPX4 knockdown did reduce tumor burden specifically in DIO but not control mice." (PMID 40001204, 2025). "In addition, glutathione peroxidase‐4 (GPX4), which can reduce the production of reactive oxygen species (ROS) and inhibit lipid peroxidation under the influence of the prosthetic group glutathione (GSH), plays a suppressive role in ferroptosis in tumour cells." (PMID 38682349, 2024). "Moreover, Treg cells lacking Gpx4 can not only induce ferroptosis in Tregs but also enhance the antitumor effect of Th17 cells through increased IL-1β, both of which are mechanisms that inhibit tumor progression." (PMID 39726588, 2024). "Importantly, lower GPX4 expression and activity were detected in RRM1 knockdown cells after radiation, suggesting that the balance between ROS and the antioxidant system was disrupted, further supporting the role of RRM1 in targeting the tumor antioxidant system to increase radiosensitivity." (PMID 35915092, 2022). "Importantly, drug-resistant tumor are more sensitive to lipid peroxidation, which undoubtedly makes, the combination of System Xc−/GSH/GPX4 axis-based ferroptosis inducers with chemotherapeutic agents may become a new strategy for the treatment of drug-resistant solid tumors." (PMID 36105219, 2022). "However, in the intervention process of ferroptosis, it was found that the application of GPX4 inhibitors could not completely block the occurrence of ferroptosis, and some ferroptosis was also found in the process of tumour intervention." (PMID 36309489, 2022). "As the current GPX4 inhibitor could not specifically recognize tumor cells, future clinical study should focus more attention on the development of compounds specifically target to GPX4 of tumor cells." (PMID 35882850, 2022). "However, GPX4 inhibition fails to trigger ferroptosis in some types of tumor cells." (PMID 36566325, 2022). "Inhibition of central in vitro ferroptosis suppressors GPX4, GCLC, or SLC7A11 across these multiple models fails to impact established tumor growth." (PMID 41959261, 2026). "We next orthotopically injected GPX4-knockdown metM-Wntlung cells or scramble control cells into the mammary fat pad of nonobese (control) and DIO mice, and monitored tumor growth." (PMID 40001204, 2025). "As a result, for GPX4, but not AR, inhibition led to ferroptosis in LAR tumours, highlighting the importance of this specific metabolic target." (PMID 40136651, 2025). "This vulnerability was recapitulated in vivo through mouse models that showed that GPX4 inhibition led to prolonged survival in CDKN2A null, but not CDKN2A WT GBM tumours." (PMID 40136651, 2025). "In vivo experiments indicate that the absence of GINS4 can suppress tumor growth in HCC, increase the expression of GPX4, and decrease the levels of Ki67, while also reducing the activity of the POLE2/PI3K/AKT signaling pathway." (PMID 40386780, 2025). "Mechanistically, BP induces ferroptosis through both canonical (ROS accumulation and GPX4 inhibition) and non-canonical (HMBOX1-mediated) pathways, effectively targeting both bulk tumor cells and cancer stem cells." (PMID 41049453, 2025). "In contrast, IR808-ATIPA, as a small-molecule iodine compound, activates the ferroptosis pathway in tumor cells, with its LPO regulated by GPX4 negative feedback, demonstrating a superior therapeutic window." (PMID 40831788, 2025). "ORP100 treatment likewise suppressed chemotherapy‐induced GPX4 and SLC7A11 downregulation in vivo in BM cells but not in tumors when evaluated in an EG7‐implanted tumor model treated with 5‐FU or in a B16‐F10 tumor‐implantation model treated with cisplatin." (PMID 40932638, 2025).
tumor (continued). "Consistently, an increase in the expression levels of GPX4 and FTH1 observed in in Tumor#1 compared to Para#1 but not in Tumor#2 compared to Para#2." (PMID 39540244, 2025). "Ferroptosis inducers (such as the GPX4 inhibitor RSL3) can lead to the elimination of M2 macrophages, but do not affect M1 macrophages, resulting in synergistic anti-tumor effects." (PMID 41035634, 2025). "GPx4 and GPx8 probably do not play an important role in CRC pathogenesis, but antioxidants are discussed as dual actors in tumor development." (PMID 35208621, 2022). "However, in some tumor cells with high expression of ACSL4, even the absence of GPX4 could not cause cell ferroptosis, which indicates that there is an antioxidant system independent of GSH/GPX4." (PMID 36408273, 2022). "Tissue microarray analysis revealed that phosphor 4EBP1 staining correlated with GPX4 level, but not ACSL4 level, in tumor samples from cancer patients." (PMID 33707434, 2021). "Interestingly, the authors showed that GPX4’s expression was dependent on androgen receptor (AR) signalling, but treating the tumours with AR inhibitors did not prime LAR tumours for ferroptosis." (PMID 40136651, 2025). "Notably, α4-1BB treatment facilitated antitumor effects of tumor-reactive WT CD8+ T cells, but not those of GPX4–/– CD8+ T cells." (PMID 40178905, 2025). "Moreover, in these tumor samples from nude mice, the expression of LAPTM4B positively correlated with expression of SLC7A11, but not GPX4." (PMID 38902268, 2024). "However, when GPX4 inhibitor ML210 and RSL3 were combined with NRF2 inhibitors TRI and CP, they did not exhibit a synergistic effect on tumor growth and ascites production reduction." (PMID 38396022, 2024). "Notably, GPX4 cKO CD8+ T cells failed to completely eradicate tumors with fewer tumor-infiltrating transferred CD8+IFN-γ+ cells compared with control CD8+ T cells." (PMID 38441967, 2024). "Expression of FSP1 and GPX4 in resected specimens from patients with ESCC was evaluated by immunohistochemistry and classified as positive or negative based on the percentage of positively tumor-stained area." (PMID 36576648, 2023). "GPX4 inhibitors, including RSL3 and DPI10, can directly inhibit the accumulation of ROS and lead to ferroptosis 15, but there has been no basic research on the relationship between GPX4-knockout tumor cells and immune cells." (PMID 34975326, 2022). "Interestingly, when comparing expression across all tumor samples versus all normal tissue samples, in contrast to SLC3A2 and SLC7A11, GPX4 was not significantly overexpressed in cancer tissues compared to normal tissues across the set." (PMID 33672555, 2021). "High GPx4 expression was significantly correlated with advanced N stage (P = 0.038), M stage (P = 0.023), and TNM stage (P = 0.023), but not with other factors such as age, gender, tumor location, Lauren type, Borrmann type, differentiated degree, T stage, HER2 status, or PD-L1 status." (PMID 39908861, 2025). "However, the GPX4 inhibitor, which acts as an antioxidant, displays greater sensitivity towards CD8+T cells and CD4+T cells, leading to a preferential induction of ferroptosis in killer T cells rather than tumor cells." (PMID 38853203, 2024).
cancer (964 papers, 2010 to 2026). A tumor composed of atypical neoplastic, often pleomorphic cells that invade other tissues. "This implies that cancer cells undergoing EMT are more susceptible to ferroptosis when GPX4 is inhibited, thereby promoting LPO." (PMID 41596341, 2026). "LPCAT3 expression strongly correlates with ferroptosis susceptibility, and its high expression in cancer cells directly predicts hypersensitivity to GPX4 inhibitors." (PMID 41601687, 2026). "Human telomerase reverse transcriptase (hTERT) and glutathione peroxidase 4 (GPX4) are overexpressed in many cancers and linked to apoptosis and ferroptosis, respectively." (PMID 41682351, 2026). "Further analysis on the response in vivo is lacking, however, tumor clearance has been associated with decreases in GPX4 levels within cancer cells." (PMID 41139700, 2026). "Present studies have also shown that an increase in GPX4 is also associated with the protection of cancer cells from cellular senescence and immune evasion." (PMID 40746894, 2025). "Emerging clinical evidence reveals significant associations between GPX4 overexpression and malignant progression across various cancers." (PMID 40746894, 2025). "Overall, the data above indicate that GLS1 and GPX4 show high levels of expression in cancer patients' tissues and are linked to unfavourable outcomes." (PMID 40259435, 2025). "Although further research is needed, triple combination comprising ALK‐TKI plus GPX4 inhibitor plus a TKI corresponding to the bypass pathway would be helpful to eliminate the cancer cells and reduce the risk of DTP induction." (PMID 39369284, 2025). "Artesunate, by blocking GPX4, can reverse sunitinib resistance and cause ferroptosis in renal cell cancer by causing the cancer to spread." (PMID 40916076, 2025). "By accelerating the degradation of GPX4, increasing intracellular Fe, and causing lipid peroxidation, bofantaline can induce ferroptosis in cancer cells." (PMID 40969276, 2025). "In terms of prognosis, GPX4 expression levels were closely associated with overall survival across various cancers." (PMID 41142608, 2025). "This study’s pan-cancer analysis reveals associations between GPX4 expression and various cancer-related factors, including prognosis, DNA methylation, TMB, MSI, immunoregulatory genes, and immune cell infiltration." (PMID 41142608, 2025). "Frustratingly, this renders cancer cells more susceptible to GPX4 inhibitors or general inducers of iron decay." (PMID 40746825, 2025). "Specifically, inactivation of DHODH in GPX4-deficient cancer cells results in mitochondrial lipid peroxidation and ferroptosis." (PMID 40959280, 2025). "GPX4 consistently exhibited strong correlations with the top 10 most-associated genes across multiple cancer types." (PMID 41142608, 2025). "A significant correlation was observed between GPX4 expression and the presence of macrophages, cancer-associated fibroblasts (CAFs), neutrophils, B cells, CD8+ T cells, and regulatory T cells (Treg) in some cancers." (PMID 41142608, 2025). "Ferroptosis is a key determinant of cancer cell susceptibility, driven by GPX4 depletion, the accumulation of redox‐active iron, and peroxidized PUFA." (PMID 40159622, 2025). "According to Cox regression, GPX4 expression levels were significantly associated with OS in six cancer types: BRCA, COAD, LAML, THCA, UCEC, and UVM." (PMID 41142608, 2025). "Studies have shown that inhibiting FSP1 can induce ferroptosis in cancer cells with GPX4 deficiency or overexpression." (PMID 39150660, 2025). "The combination of low GSH levels and GPX4 activity in ARID1A-deficient cancer cells is thought to significantly increase the susceptibility to ferroptosis." (PMID 40369167, 2025). "The up-regulation of ACSL4 expression and enhancement of lipid peroxidation rate induced by RB1 loss further intensify cancer cell dependence on GPX4 for iron homeostasis blockade." (PMID 40746825, 2025).
cancer (continued). "DHO protects cells from RSL3-induced ferroptosis, and the DHODH inhibitor brequinar (BRQ) is able to promote ferroptosis in GPX4-deficient cancer cells." (PMID 41293165, 2025). "In an acidic TME, progressive breakdown of MIL-101(Fe)@RSL3 released Fe3+ and RSL3, which aggravates ferroptotic cell death in cancer cells by causing iron overload and blocking GPX4." (PMID 39276361, 2024). "These regulatory mechanisms governing GPX4 levels and activity have shown promising potential in preclinical studies for treating diseases associated with iron overload, especially cancer cells." (PMID 38650929, 2024). "FSP1 is associated with poor prognosis in malignant tumors and, together with GPX4, is considered an important target for cancer treatment." (PMID 39062119, 2024). "Cancer cell lines across different tissue types exhibit a wide range of susceptibilities to GPX4 inhibitors such as ML210, suggesting alternative pathways that regulate ferroptosis sensitivity." (PMID 39188677, 2024). "Inhibition of GPX4 leads to mitochondrial lipid peroxidation and ferroptosis in cancer cells with a deficiency of GPD2." (PMID 37548939, 2024). "Although mitochondrial GPX4 has the most associations with inhibiting ferroptosis in cancer cells, cytosolic GPX4 is expressed in all cell types and was the only isoform able to rescue embryonic lethality of GPX4 deletion in mice." (PMID 39188677, 2024). "In GPX4-deficient cancer cells, DHODH inactivation leads to extensive lipid peroxidation and ferroptosis." (PMID 39192972, 2024). "The increased association of mitochondrial GPX4 with cancer cells is likely due to the complex relationship between mitochondrial activity and ferroptosis." (PMID 39188677, 2024). "GPX4 is a central mediator of cancer cell death and is associated with the production of lipid ROS for ferroptosis." (PMID 38756246, 2024). "Elevated ROS production and elevated iron requirements make cancer cells more susceptible to ferroptosis, and high levels of GPX4 expression can be an inhibition factor in the development of ferroptosis." (PMID 39125992, 2024). "The deletion of GPD2 in cancer cells heightens their sensitivity to mitochondrial lipid peroxidation and ferroptosis caused by GPX4 inhibition." (PMID 38540171, 2024). "The regulatory mechanism of GPX4 expression in cancer cells has been studied; however, the underlying mechanism is complicated due to the unique regulation of its translation system, and thus it remains poorly elucidated." (PMID 38182643, 2024). "Conversely, the upregulation of GPX4 has been linked to increased resistance of cancer cells to ferroptosis, presenting a potential target for therapeutic intervention." (PMID 38469234, 2024). "Ferroptosis suppressor protein 1 (FSP1) is a key protein in a newly identified ferroptosis-protective mechanism that occurs in parallel with the GPX4-mediated pathway and is associated with chemoresistance in several cancers." (PMID 38374229, 2024). "Conventional chemotherapy or radiation therapy can cause cancer cells to die when xCT and GPX4 are inhibited." (PMID 39544291, 2024). "Inhibition or inactivation of DHODH has been linked to the promotion of ferroptosis in cancer cells characterized by low mitochondrial GPX4 expression." (PMID 39568772, 2024). "Previously, we mentioned GPX4’s research on cancer; in a new study, it was found that the loss of GPX4 leads to an excessive buildup of lipid peroxides and ferroptosis in Treg cells when T cell receptor/CD28 co-stimulation occurs." (PMID 38962561, 2024). "Conversely, increased GPX4 expression is linked to heightened resistance to ferroptosis in cancer cells." (PMID 38469234, 2024). "The study found that GPX4 inhibits both ferroptosis and apoptosis, and that CircDTL causes cancer through the circDTL/miR-1287-5p/GPX4 axis." (PMID 38887390, 2024).